GLI1 (GLI family zinc finger 1)
Diseases named in the same sentence as GLI1 in open-access papers (continued):
Sharing a sentence is not in itself a finding about the gene and the disease.
Gorlin-Goltz syndrome (2 papers, 2015 to 2025). "Patients with basal cell nevus syndrome (BCNS or Gorlin syndrome) carry germline mutations in one allele of PTCH1 that leads to unrestrained activation of GLI1 and an ensuing predisposition for spontaneous tumorigenesis." (PMID 26197339, 2015).
graft versus host disease (2 papers, 2013 to 2020). An immune system disorder that occurs after allogeneic hematopoietic stem cell transplant and is a reaction of donor immune cells against host tissues. "We and others have shown that GLI1 and GLI2 are upregulated in SSc skin and fibroblasts and SHH pathway activation plays an important role in the pathogenesis of tissue fibrosis both in scleroderma and sclerotic graft versus host disease (GVHD)." (PMID 33303026, 2020).
Helicobacter infection (2 papers, 2013 to 2023). "In the current study, we examined the role of Gli1 during chronic Helicobacter infection and found that Gli1 was required for SPEM to develop." (PMID 23520544, 2013). "Moreover, Slfn4 expression has been linked to aberrant myelopoiesis, making it a relevant regulatory gene contributing to generation of the various Gli1-dependent myeloid populations during Helicobacter infection." (PMID 23520544, 2013).
inflammatory breast carcinoma (2 papers, 2011 to 2014). An advanced, invasive breast adenocarcinoma characterized by the presence of distinct changes in the overlying skin. "Targeting GLI1 in inflammatory breast cancer has been shown to decrease the migratory ability of these cells, and to increase apoptosis." (PMID 25252859, 2014).
keloid (2 papers, 2013 to 2023). An irregularly shaped, elevated mark on the skin caused by deposits of excessive amounts of collagen during wound healing. "Inhibition of the SHH signal transducer SMO inhibited the expression of GLI1 and its downstream genes and the pathologic phenotype of keloid lesions." (PMID 38062202, 2023). "We found that the secretion of SHH and expression of GLI1 and its target genes are high at the keloid margins, where cell proliferation is very active." (PMID 38062202, 2023). "Although no direct involvement of the Hedgehog and Notch signaling pathways in keloid pathogenesis has been suggested, Gli-1 has been shown to be upregulated in keloids." (PMID 23052205, 2013). "Furthermore, the HEDGEHOG (HH) signal and its downstream transcription factor GLI1 were upregulated in keloid patient–derived stem-like cells." (PMID 38062202, 2023). "In this study, we found that the HH signaling pathway and its downstream effector, the transcription factor GLI1, are activated in keloid stem-like cells derived from patients and suppression of HH signaling inhibits keloid-like tissue progression in a mouse transplantation assay." (PMID 38062202, 2023). "Thus, the expression and function of these protein modifiers and/or transcriptional cofactors of GLI1 may be different among keloid sites, and these differences may influence the expression of the keloid fibroproliferative phenotype." (PMID 38062202, 2023). "Upstream regulator analysis revealed that the expression of several molecules involved in GLI1 activation was elevated in these three types of stem-like cells in keloid patients, although not completely identical." (PMID 38062202, 2023). "Because GLI1-inducing signals were upregulated in three different keloid-derived stem-like cells (KNS, KMS and KCS), SHH may be a major inducer of GLI1 in keloids." (PMID 38062202, 2023). "The expression of PTCH1 was enhanced in GLI1-upregulated keloid-derived stem-like cells but not in fibroblasts from keloid tissues, suggesting that the response to SHH differs between mature fibroblasts and stem-like cells." (PMID 38062202, 2023).
malignant mesothelioma (2 papers, 2023 to 2025). A malignant neoplasm of the pleura or peritoneum, arising from mesothelial cells. "Timer database analysis revealed that immune cell infiltration mechanisms in malignant mesothelioma were closely associated with SMO and GLI1 expression." (PMID 37139482, 2023). "Among GLI1 gene expression in malignant mesothelioma, B cells and macrophages were positively correlated with GLI1 gene expression, and the remaining immune cells were negatively correlated with GLI1 gene expression (P < 0.05)." (PMID 37139482, 2023). "In conclusion, this study analyzed the relationship between SMO and GLI1 expression prognosis and immune cell infiltration mechanisms in malignant mesothelioma tissues by immunohistochemistry, RT-qPCR, and bioinformatics." (PMID 37139482, 2023).
mental disorder (2 papers, 2013 to 2019). A disease that has its basis in the disruption of mental process. "Lithium, a clinical mood stabilizer for mental disorders, potently inhibits the activity of glycogen synthase kinase 3β (GSK3β) that promotes the ubiquitin-dependent proteasome degradation of GLI1, an important downstream component of hedgehog signaling." (PMID 23626687, 2013).
metastatic cancer (2 papers, 2012 to 2016). A carcinoma which has spread from the original site of growth to another anatomic site. "Similarly, the staining intensity of GLI1 in tissues from invasive cancer and from metastatic cancer were significantly greater (p<0.0001) compared to normal tissues." (PMID 22479615, 2012). "More importantly, the expression of Oct4, Sox2, Gli1, CD44, CD133, p-AKT, and p-ERK was significantly higher in metastatic cancer tissues than in primary cancer tissues." (PMID 26769843, 2016).
myeloid malignancies (2 papers, 2019 to 2021). "In myeloid malignancies, the MDS cell MDS-L has been found to be resistant to glasdegib, but the inhibition of GLI1 by siRNA-mediated knockdown or the GLI1 antagonist, GANT61, inhibits cell proliferation." (PMID 34638372, 2021).
myxoid liposarcoma (2 papers, 2025). A liposarcoma characterized by the presence of round non-lipogenic primitive mesenchymal cells and small signet ring lipoblasts within a myxoid stoma with a branching vascular pattern. "In this case, the FISH study for DDIT3/GLI1 was within the reference range, which is more relevant for excluding myxoid liposarcoma." (PMID 40084340, 2025). "Fluorescence in situ hybridization (FISH) for DDIT3/GLI1 (12q13.3) was within the reference range, ruling out myxoid liposarcoma." (PMID 40084340, 2025).
oral cancer (2 papers, 2024 to 2025). "The PRKD1 E710D hotspot mutation and protein expression of PRKD1 and HH components (SHH, IHH, SMO, and GLI‐1) were detected in PAC regardless of tissue invasion, although HH proteins contributed to the morphogenesis of this rare oral cancer." (PMID 40930949, 2025).
ovarian epithelial tumor (2 papers, 2013 to 2025). A benign, borderline, or malignant tumor that originates from the surface epithelium of the ovary. "While GLI1 was mainly distributed in the cytoplasm of ovarian epithelial tumors, a high level of GLI1 expression in invasive cancer samples was associated with scattered nuclear GLI1 immunoreactivity." (PMID 39856733, 2025). "While Gli1 expression was mainly observed in the cytoplasm of ovarian epithelial tumors, a high level of Gli1 expression in invasive cancer samples was associated with scattered nuclear Gli1 immunoreactivity." (PMID 23303278, 2013).
papillary thyroid carcinoma (2 papers, 2018 to 2024). "For instance, LINC00641 destabilized GLI1 mRNA through interacting with RPB IGF2BP1, thereby suppressing malignant traits of papillary thyroid carcinoma cells." (PMID 39425009, 2024).
pituitary adenomas (2 papers, 2016 to 2021). "However, this information is of great importance because GLI1 and SHH are highly expressed by GH-, PRL- and ACTH-expressing human pituitary adenoma, which suggests that HH signaling has an impact on pituitary tumor formation." (PMID 33480359, 2021). "However, although human ACTH, GH or PRL-expressing pituitary adenoma show very high expression of the HH signaling inducer SHH and the HH target gene GLI1, a direct link between Hh signaling (e.g. mutations or pathway overactivation) and tumor formation in the AL has not been confirmed." (PMID 33480359, 2021).
pituitary tumor (2 papers, 2021 to 2023). A benign or malignant neoplasm affecting the pituitary gland. "Since ACTH-, GH- and PRL-immunopositive PitNETs show the highest SHH and GLI1 levels, we propose that HH signaling activity may play a role in formation and/or maintenance of these pituitary tumor subtypes as it is known for classical HH-associated tumors." (PMID 37476499, 2023).
prostate adenocarcinoma (2 papers, 2015 to 2017). "The mean of composite score values obtained for GLI-1 expression in malignant epithelial cells in prostatic adenocarcinoma specimens (1.9 ± 0.3) was significantly higher as compared to the value for normal tissues (0.4 ± 0.3; *p < 0.0005)." (PMID 25682877, 2015). "Moreover, the expression level of GLI-1 was also higher in prostatic adenocarcinomas and mainly detected in the nuclei and cytoplasm of PC cells (indicated by arrows)." (PMID 25682877, 2015). "Similarly, an enhanced expression of the transcription factor of the hedgehog cascade, GLI-1 was also observed in 47% of 76 cases of prostatic adenocarcinomas." (PMID 25682877, 2015). "However, different from other tumors such as human MB and prostate adenocarcinoma, neither enhancing expression of p27Kip1 nor antagonizing Hedgehog signaling by regulating Gli1 has be found in HCC cells after KCTD11 overexpression (data not shown)." (PMID 28465479, 2017). "Importantly, the immunohistochemical analyses have indicated that the increased expression levels of SHH and GLI-1 frequently occur in prostatic adenocarcinoma tissue specimens relative to non-malignant prostate tissues." (PMID 25682877, 2015).
psoriasis (2 papers, 2017 to 2023). An autoimmune condition characterized by red, well-delineated plaques with silvery scales that are usually on the extensor surfaces and scalp. "Several studies have previously proved the association between candidate genes involved in metabolic pathways of acitretin and the pathogenic mechanism of psoriasis, such as CSMD1, CCHCR1, GLI1, SFRP4 etc.." (PMID 28146080, 2017).
salivary gland tumors (2 papers, 2024 to 2025). "Similarly, the predominantly nuclear expression of protein GLI‐1 was also found in other salivary gland neoplasms, including basal cell adenocarcinoma." (PMID 40930949, 2025). "Other salivary gland tumors, such as pleomorphic adenoma, adenoid cystic carcinoma, and mucoepidermoid carcinoma, are characterized by strictly cytoplasmic and nuclear expression of SHH and GLI‐1, respectively." (PMID 40930949, 2025).
Sepsis (2 papers, 2024 to 2025). Sepsis is defined as life-threatening organ dysfunction caused by a dysregulated host response to infection. "Mechanistically, IL-6 and ROS synergistically sustained the phosphorylation of STAT3 during early sepsis, thereby initiating the activation of the Shh pathway, by which the binding of Gli1 is potentiated to the Dio3 promoter." (PMID 39877839, 2025). "Notably, the Shh/Gli1 pathway predominantly regulates Dio3 in skeletal muscles and lung tissues upon early sepsis." (PMID 39877839, 2025). "In sepsis, RELA, CEBPB, NFKBIA, STAT6, IRF8 and SPI1 were downregulated, with no significant change in NFKB1, JUN and GLI1." (PMID 39444551, 2024).
synovial sarcoma (2 papers, 2021 to 2024). "Genetic alterations supporting the genetic diagnosis were identified in four of the five patients, including EWSR1-ATF1 in clear cell sarcoma, PTCH1-GLI1 in GLI1-rearranged tumor, SS18-SSX2 in synovial sarcoma, and SMARCA4-THOP1 in SMARCA4-deficient undifferentiated sarcoma." (PMID 34131151, 2021).
T cell lymphomas (2 papers, 2017 to 2021). "This agrees with a previous study showing that GLI1 knockdown or inhibition leads to a reduction in pSTAT3 levels in T cell lymphomas including CTCL." (PMID 34282785, 2021). "Pharmacological inhibition or genetic interference targeting GLI1 provided potential therapeutic strategies to improve the poor prognosis of T-cell lymphomas." (PMID 27275540, 2017). "It was worth mentioning that Fisher's exact probability test of the immunochemical results showed both p-STAT3 and SOCS3 protein expression were positively correlated with GLI1 in T-cell lymphomas with each P value<0.05." (PMID 27275540, 2017). "Analysis results showed that both p-STAT3 and SOCS3 protein expression were positively correlated with GLI1 in T-cell lymphomas with the P value as 0.06 and 0.021 respectively." (PMID 27275540, 2017). "Moreover, the protein expressions of p-STAT3 and SOCS3 were positively correlated with GLI1 in T-cell lymphomas." (PMID 27275540, 2017). "We decided to determine the effect of NT1721 on STAT3 activation since several reports show that GLI1 inhibition or knockdown decreased phosho-STAT3 (pSTAT3) levels in T cell lymphomas and that pSTAT3 may be an important driver of CTCL, especially in advanced disease." (PMID 34282785, 2021). "We examined the expression of GLI1, p-STAT3, STAT3 and SOCS3 for tissues from 35 cases of T-cell lymphomas by immunohistochemistry, in comparation with the control of 15 cases of reactive hyperplasia of lymph node (RHL)." (PMID 27275540, 2017). "The physical interaction of GLI1 and p-STAT3 in the three T-cell lymphoma cells were demonstrated by Western blot analysis of Co-IP." (PMID 27275540, 2017). "In order to explore the potential connections between Hh/GLI1 and STAT3/SOCS3 pathways in T-cell lymphomas, those immunohistochemical results were incorporated into the Fisher's exact probability test." (PMID 27275540, 2017). "The expressions of GLI1, p-STAT3, STAT3, and SOCS3 were detected respectively in 28/35(80.0%), 26/35(74.2%), 32/35(91.4%), and 24/35(68.6%) of T-cell lymphoma cases, when tumors displaying staining in 30% or more of the cells were categorized as positive cases." (PMID 27275540, 2017). "Aberrant activation of Hh/GLI1 and STAT3 pathways usually occur in tumors, however their crosstalk is quite unknown in T cell lymphomas." (PMID 27275540, 2017). "We speculated that activation of GLI1 could activate p-STAT3 and SOCS3 expression directly or indirectly, and thereby activated Hh signaling resulting in T-cell lymphoma cell ontogeny." (PMID 27275540, 2017). "This study mainly focuses on the Hh/GLI1 and STAT3/SOCS3 pathways in T-cell lymphomas." (PMID 27275540, 2017).
ulcerative colitis (2 papers, 2020 to 2023). An inflammatory bowel disease involving the mucosal surface of the large intestine and rectum. "In humans, a GLI1 nonsynonymous polymorphism is strongly associated with ulcerative colitis, where areas of colonic inflammation display reduced expression of the HH target genes GLI1, PTCH, and HHIP." (PMID 32196081, 2020). "We first analyzed the expression levels of GLI1, IL-1A, and IL-1B with the published dataset and found that they were increased in ulcerative colitis compared to health tissues." (PMID 37889976, 2023).
viral infection (2 papers, 2021 to 2022). "Emerging evidence suggests that viral infections can also regulate the expression of intercellular junction proteins by Gli1, a transcription factor in the Shh pathway." (PMID 35233032, 2022).
-dependent (1 paper, 2016). "Similarly, the small molecule Glabrescione B has been shown to interfere with the Hedgehog pathway by inhibiting GLI1/DNA interaction in preclinical models of Hedgehog-dependent tumors." (PMID 27095580, 2016).
ACTHomas (1 paper, 2020). "SHH and its target gene GLI1 were also shown to be overexpressed in GHomas, ACTHomas, and prolactinomas, further supporting that excess SHH signaling is involved in the development/maintenance of hormone-producing PAs." (PMID 32153500, 2020).
acute pancreatitis (1 paper, 2012). An acute inflammatory process that leads to necrosis of the pancreatic parenchyma. "Molecular biological studies showed that autocrine Shh signaling activated the key transcriptional factor Gli1 so that the target gene IL-10 was upregulated, leading to the protective and anti-inflammatory functions in the mouse model of acute pancreatitis." (PMID 22956998, 2012). "Molecular biological studies show that autocrine Shh signaling activates the key transcriptional factor Gli1 so that the target gene IL-10 is upregulated, leading to the protective and anti-inflammatory functions in the mouse model of acute pancreatitis." (PMID 22956998, 2012). "Specially, the mRNA level of Gli1 and Ptch1 all augmented as high as 20 folds compared with PBS control, which indicated that the initiation and upregulation of autocrine Shh signaling loop during the progression of acute pancreatitis in mice was established in our study." (PMID 22956998, 2012).
adenovirus infection (1 paper, 2020). "(D) Expression of Gli1 and Ptch1 in Dyrk2-/- MEFs overexpressing human DYRK2 or DYRK2-K251R (kinase dead) constructs via adenovirus infection was measured by qPCR." (PMID 32758357, 2020).
adrenal hypoplasia (1 paper, 2023). "We performed gene expression, cellular analyses, and reporter assays to demonstrate that DAX1 (dosage-sensitive sex reversal adrenal hypoplasia congenital critical region on X chromosome, gene 1) interacts with GLI1 and GLI2, the master regulators of Hh signaling." (PMID 37504255, 2023).
Alzheimer disease (1 paper, 2021). A progressive, neurodegenerative disease characterized by loss of function and death of nerve cells in several areas of the brain leading to loss of cognitive function such as memory and language. "On the other hand, a massive shortfall in PTCH1 and GLI1 was observed in the hippocampus of aged Alzheimer disease transgenic mice that would compromise the ability of genesis in both NSC and glial precursor cells." (PMID 34830484, 2021).
ankylosis (1 paper, 2024). Fixation and immobility of a joint. "Loss of Fgfr1 in Gli1+ progenitors leads to hyperproliferation and differentiation, which causes narrowed periodontal ligament (PDL) space with abnormal cementum/bone formation leading to ankylosis." (PMID 38910207, 2024).
Arthritis (1 paper, 2023). Inflammation of a joint. "This evidence suggested that inhibiting the activity of GLI1 significantly reduced the occurrence and development of arthritis in CIA mice." (PMID 37929702, 2023).
astrocytic tumor (1 paper, 2010). A glial tumor of the brain or spinal cord showing astrocytic differentiation. "A majority of the cell lines displayed low levels of PAX6 despite high GLI1 expression, as was similarly seen in primary astrocytic tumor samples." (PMID 21059263, 2010). "Interestingly, most of the astrocytic tumor samples showed low expression levels of PAX6 even though GLI1 was expressed at high levels." (PMID 21059263, 2010). "Interestingly, there was a distinct pattern of Plakoglobin expression amongst astrocytic tumor samples: low-grade samples expressed Plakoglobin, while a few high-grade samples also showed high expression levels of Plakoglobin in absence of GLI1 transcript." (PMID 21059263, 2010). "Thus, GLI1 does not appear to up-regulate PAX6 expression in astrocytic tumors." (PMID 21059263, 2010). "There was a distinct pattern of Plakoglobin expression in astrocytic tumor samples: low-grade (AII) samples did not express Plakoglobin and few high-grade samples highly expressed Plakoglobin in the absence of GLI1 mRNA expression." (PMID 21059263, 2010).
autoimmune hepatitis (1 paper, 2015). Hepatitis caused by autoantibodies. "Pretreatment with resveratrol ameliorated the pathologic effects of ConA-induced autoimmune hepatitis and significantly inhibited IL-2, IL-6, TNF-α, Shh, Gli-1, and Ptc." (PMID 26089871, 2015).
B-cell non-Hodgkin lymphoma (1 paper, 2017). The most common type of non-Hodgkin lymphoma. "Such epigenetic markers promote GLI-1 occupation of ABCG2 gene promoter sequences and induce the expression of ABCG2, which is involved in chemoresistance in the presence of doxorubicin and methotrexate in non-solid tumors and B-cell non-Hodgkin lymphoma cells." (PMID 28978016, 2017).